RNU6-553P (RNA, U6 small nuclear 553, pseudogene)
Gene: Small nuclear RNA gene on chromosome 4 (105,406,997 to 105,407,092, forward strand). Ensembl gene ENSG00000200917.
Homologues: Orthologues: chimpanzee U6 (96% identical), rabbit U6 (88% identical), guinea pig U6 (75% identical). Paralogues in human: RNU6-43P (91% identical), RNU6-11P (90% identical), RNU6-28P (90% identical), RNU6-37P (90% identical), RNU6-20P (89% identical), RNU6-25P (89% identical), RNU6-29P (89% identical), RNU6-1 (88% identical), RNU6-1091P (88% identical), RNU6-1216P (88% identical), RNU6-2 (88% identical), RNU6-222P (88% identical), and 1286 more.